SS18 (SS18 subunit of BAF chromatin remodeling complex)
Diseases named in the same sentence as SS18 in open-access papers (continued):
Sharing a sentence is not in itself a finding about the gene and the disease.
synovial sarcoma (continued). "Synovial sarcoma (SS) is driven by a unique t(18;X) chromosomal translocation resulting in expression of the SS18-SSX fusion oncoprotein, a transcriptional regulator with both activating and repressing functions." (PMID 39550391, 2024). "Synovial Sarcomas (SS) are characterized by the presence of the SS18::SSX fusion gene, which protein product induce chromatin changes through remodeling of the BAF complex." (PMID 39257029, 2024). "FYN is a tyrosine kinase that promotes cancer growth, metastasis and therapeutic resistance, but SS18-SSX appears to negatively regulate FYN expression in synovial sarcoma cells." (PMID 39045458, 2024). "In clinical practice, synovial sarcoma is primarily identified using a combination of histological evaluation, molecular testing for SS18-SSX fusion, and IHC markers such as TLE1." (PMID 39518009, 2024). "Synovial sarcoma (SyS) is an aggressive soft-tissue malignancy characterized by a pathognomonic chromosomal translocation leading to the formation of the SS18::SSX fusion oncoprotein." (PMID 38798672, 2024). "It is worth noting that two SSX genes, namely, SSX1 and SSX2, are found to commonly be fused to SS18 in synovial sarcoma patients." (PMID 39045458, 2024). "SS18 break-apart fluorescence in situ hybridization (FISH) is frequently used as an adjunct for diagnosing synovial sarcoma." (PMID 38982505, 2024). "Although synovial sarcoma is characterized by a simple karyotype and a translocation involving SS18 and SSX1, 2, or 4, omics studies are particularly crucial for patients who share the same karyotype but exhibit differing clinical prognoses." (PMID 39735532, 2024). "In parallel with mechanistic studies, transgenic mouse experiments have validated the SS18-SSX fusion as a putative oncogenic driver in synovial sarcoma." (PMID 39045458, 2024). "EGR1 is a direct target of SS18-SSX and its transcription level is negatively correlated with SS18-SSX activity in synovial sarcoma cells." (PMID 39045458, 2024). "Lastly, a fourth patient with MPNST was reclassified as having synovial sarcoma based on detecting an SS18::SSX2 fusion, leading to an evaluation for NY-ESO-1-based T-cell therapy." (PMID 38228904, 2024). "Synovial Sarcoma (SS) is driven by the SS18::SSX fusion oncoprotein and is ultimately refractory to therapeutic approaches." (PMID 38883782, 2024). "Genetically, synovial sarcoma has a specific t(X;18)(p11.2;q11.2) gene translocation and produces the SS18-SSX fusion gene." (PMID 39735532, 2024). "When synovial sarcoma is considered by immunohistochemistry and SS18 translocation is detected by FISH, synovial sarcoma can be diagnosed." (PMID 39162837, 2024). "In recent years, immunohistochemistry has played an important role in aiding the diagnosis of synovial sarcoma, particularly through the identification of the more specific marker, SS18-SSX." (PMID 39518009, 2024). "SS18 gene rearrangement was confirmed by fluorescence in situ hybridization, and the tumor was diagnosed as synovial sarcoma." (PMID 36860358, 2023). "Synovial sarcoma (SS) is a soft tissue sarcoma showing variable epithelial differentiation and is characterized by SS18::SSX1, SSX2, or SSX4 fusions." (PMID 36941503, 2023). "While BAF complexes are critical in SS18-SSX-driven synovial sarcomas, we show that EWSR1 and MN1 activate gene expression via a mechanism that can be independent of BAF presence." (PMID 37735617, 2023). "Classically, the diagnosis of synovial sarcoma is confirmed by demonstrating the SS18 gene translocation by FISH." (PMID 37370803, 2023). "The SS18-SSX fusion drives oncogenic transformation in synovial sarcoma by bridging SS18, a member of the mSWI/SNF (BAF) complex, to Polycomb repressive complex 1 (PRC1) target genes." (PMID 37735617, 2023).
synovial sarcoma (continued). "Synovial sarcoma is associated with translocation causing a fusion between chromosomes SSX1, SSX2, and SSX4 and chromosome SS18, occurring in more than 90% of synovial sarcoma cases leading to the formation of SSX-SS18 oncogenes." (PMID 38188535, 2023). "The cytogenetic testing showed a chromosomal translocation in the SS18 gene at 18q11.2, consistent with the diagnosis of primary synovial sarcoma." (PMID 38188535, 2023). "This highlights the critical role of the SSXRD domain in the precise recruitment of SS18-SSX at specific synovial sarcoma gene targets." (PMID 37735617, 2023). "Certain subtypes are strongly associated with genetic fusions, such as Ewing’s sarcoma (EWSR1::FLI1), alveolar rhabdomyosarcoma (PAX3/7::FOXO1), and synovial sarcoma (SS18::SSX1/2/4)." (PMID 36980578, 2023). "The BRG1/BAF complex and its interaction with the SS18-SSX fusion protein emerged as significant molecular features in synovial sarcoma." (PMID 37686615, 2023). "Our data show that PRC1.1 acts as the main depositor of H2AK119ub1 in synovial sarcoma cells and is therefore needed for SS18-SSX chromatin binding." (PMID 37735617, 2023). "In the diagnosis of soft tissue and bone tumors, NGS can be very helpful, because some gene fusions seem to be tumor-specific (for example, the SS18–SSX gene fusion in synovial sarcoma)." (PMID 38137051, 2023). "These forms always require confirmation by FISH FISH for X:18 was performed for 37 cases diagnosed with synovial sarcoma, and the rearrangement of the SS18 gene was detected in 24 patients (65%)." (PMID 36164527, 2022). "Retrospective fluorescent in-situ hybridisation analysis of original histology also revealed a SS18 gene rearrangement consistent with a diagnosis of synovial sarcoma." (PMID 36456921, 2022). "Together with BAF47, SS18 regulates normal expression patterns from enhancers and promoters; however malignant gene translocation (SS18-SSX) in synovial sarcoma evicts BAF47 from the complex and new fusion oncoprotein activates bivalent genes." (PMID 35973998, 2022). "The EWRS1 fusion corresponded to Ewing sarcoma (FL1 gene) and EMCS (NR4A3 gene), and the SS18-SSX fusion corresponded to synovial sarcoma, as would be expected." (PMID 36430703, 2022). "On this basis, the FISH was repeated on the original 2013 tumour which also showed an SS18 gene rearrangement consistent with the diagnosis of synovial sarcoma in the original tumour." (PMID 36456921, 2022). "Histological analysis of the recurrence revealed a spindle cell tumour with a SS18 gene rearrangement consistent with synovial sarcoma." (PMID 36456921, 2022). "Synovial sarcoma is an uncommon soft tissue tumor of soft tissue, characterized by a specific SS18 rearrangement." (PMID 35820955, 2022). "Our data demonstrate that both LLPS and assembling into chromatin remodelers contribute to the oncogenic activity of SS18-SSX in synovial sarcomas." (PMID 35585082, 2022). "Approximately 90% of synovial sarcomas have the t(x;18) chromosomal translocation, SS18/SSX, that combines the activation domain of SS18 and the repressor domain of SSX." (PMID 36686841, 2022). "The tumor was resected and confirmed to be a monophasic synovial sarcoma with a SS18-SSX gene fusion." (PMID 35422025, 2022). "We have addressed the mechanisms by which the fusion protein SS18-SSX modifies the epigenome toward the development of synovial sarcoma and the establishment of its potentially targetable vulnerabilities." (PMID 33361335, 2021). "Multiple biopsies with immunohistochemical analysis and fluorescence in situ hybridization showed a rearrangement of SS18 gene, indicative for synovial sarcoma." (PMID 33648512, 2021). "Two peptides derived from the SS18-SSX gene fusion in synovial sarcoma showed specific binding to HLA-A24 molecules." (PMID 34440251, 2021). "SS18 encodes a subunit of the SWI/SNF (BAF) complex and this gene is often rearranged in synovial sarcoma." (PMID 34381020, 2021).
synovial sarcoma (continued). "For example, results similar to the ones presented here were recently published for synovial sarcoma, which expresses the chimeric oncogene SS18-SSX." (PMID 34573355, 2021). "The resulting chimeric SS18–SSX fusion proteins play a crucial role in the tumorigenesis of synovial sarcoma." (PMID 34440844, 2021). "Synovial sarcomas have unique genomic characteristics and are driven by a pathognomonic t(X;18) chromosomal translocation and subsequent formation of the SS18:SSX fusion oncogenes." (PMID 34069748, 2021). "In synovial sarcoma, SS18 is commonly fused to a portion of the SSX protein, destroying its ability to act as a tumor suppressor." (PMID 34445083, 2021). "Synovial sarcoma is characterized by a specific chromosomal translocation t(X;18)(p11;q11) with SS18-SSX fusion gene." (PMID 32867125, 2020). "Barham and colleagues provided direct evidence for involvement of Wnt signaling in the SS18-SSX-mediated carcinogenesis of synovial sarcoma." (PMID 32429395, 2020). "Synovial sarcoma is a simple karyotype defined by the translocation t(X,18) (p11, q11), which results in an SS18-SSX fusion protein that disrupts epigenetic regulation." (PMID 33072594, 2020). "Dysfunctional BAF-complexes have a specific relevance in synovial sarcoma, since the disease is driven by SS18-SSX fusion oncogenes." (PMID 33371192, 2020). "Detection of SS18-SSX fusion transcripts is diagnostic and particularly valuable in synovial sarcomas arising in atypical locations outside the extremities." (PMID 32867125, 2020). "Studies on RT and synovial sarcomas established that defects in SWI/SNF subunits SMARCB1 and SS18 cause cancer." (PMID 31123059, 2019). "BRD9 is a component of SS18-SSX containing BAF complexes in synovial sarcoma cells; and integration of BRD9 into these complexes is critical for cell growth." (PMID 30431433, 2018). "As such by combining genomic and proteomic approaches we have identified BRD9 as a functional dependency within SS18-SSX fusion protein containing BAF complexes in synovial sarcoma cells." (PMID 30431433, 2018). "Synovial sarcoma is defined by a characteristic translocation t(X;18)(p11.2;q11.2), which is observed in > 95% of cases and results in the fusion of SS18 to the SSX1, SSX2, or SSX4 genes." (PMID 29415665, 2018). "This patient had biopsy-proven metastatic synovial sarcoma with a known SS18/SSX1 fusion gene on molecular testing of the primary lesion." (PMID 30128716, 2018). "In essentially 100% of MRTs SNF5 is subject to biallelic inactivation; while in synovial sarcoma assembly of SS18-SSX into BAF complexes leads to eviction and proteasomal degradation of SNF5." (PMID 30431433, 2018). "The search for the SS18 gene rearrangement gives a reliable diagnosis: the presence of a SS18 gene rearrangement in synovial sarcomas and the absence in MPNSTs." (PMID 29621151, 2018). "Synovial sarcoma tumours contain a characteristic fusion protein, SS18-SSX, which drives disease development." (PMID 30431433, 2018). "SS18-SSX dominantly assembles into BAF complexes in synovial sarcoma cells, leading to eviction of the wildtype SS18 and SNF5 proteins from the complex." (PMID 30431433, 2018). "(A) Silver stains of endogenous SS18-SSX fusion protein immunoprecipitations performed on nuclear protein lysates prepared two independent synovial sarcoma cell lines." (PMID 30431433, 2018). "Our data indicate that through assembly into SS18-SSX containing complexes BRD9 supports oncogenic gene expression programs necessary for synovial sarcoma oncogenesis." (PMID 30431433, 2018). "This work demonstrates that direct targeting of oncogenic, SS18-SSX containing BAF complexes is a viable therapeutic approach in synovial sarcoma." (PMID 30431433, 2018). "This work highlights the first actionable therapeutic vulnerability, directly linked to SS18-SSX, in synovial sarcoma." (PMID 30431433, 2018).
synovial sarcoma (continued). "RNA expression at gene targets previously shown to be directly repressed by SS18-SSX activity is reactivated by quisinostat treatment in six synovial sarcoma cell lines." (PMID 28056055, 2017). "In this study we show that HDAC inhibition by quisinostat is able to dissociate the driving complex in synovial sarcoma, resulting in reactivated expression of tumor suppressors otherwise repressed by SS18-SSX." (PMID 28056055, 2017). "We also identified previously reported fusions of SSX with SS18 in synovial sarcoma, as well as HMGA2 in liposarcoma." (PMID 28424409, 2017). "Another miRNA that is overexpressed in synovial sarcoma is miR-17, which is induced by the SS18-SSX fusion gene and is organised in a cluster (miR-17-92 cluster)." (PMID 28895916, 2017). "SS18-SSX/TLE1 complex assembly following HDAC inhibition was assessed by proximity ligation signal in five synovial sarcoma cell lines and was confirmed by co-immunoprecipitation." (PMID 27120803, 2016). "The SS18-SSX fusion in synovial sarcoma is known to disrupt the SWI/SNF assembly, resulting in SMARCB1-deficient complexes." (PMID 27783942, 2016). "Dissociation of the SS18-SSX/TLE1 complex following HDAC inhibition correlates with apoptotic induction in synovial sarcoma cell lines." (PMID 27120803, 2016). "SS18 and SS18L1 encode transcriptional regulators and are breakpoints in chromosomal translocations in synovial sarcoma." (PMID 27807467, 2016). "Chromatin immunoprecipitation revealed a decrease in HDAC1 and H3K23me3 at the EGR1 promoter, a known target for repression by the SS18-SSX/TLE1/ATF2 complex consistent with a disruption of the biologic effects on SS18-SSX target genes in synovial sarcoma." (PMID 27120803, 2016). "Synovial sarcoma is an aggressive soft tissue sarcoma genetically defined by the fusion oncogene SS18-SSX." (PMID 27125524, 2016). "Quantification of SS18/TLE1 PLA signals in synovial sarcoma cell line nuclei is more than 10-fold higher than the level seen in control cell lines." (PMID 27120803, 2016). "In this study, the proximity ligation assay was applied to a neoplasm driven by a fusion oncoprotein, in this case confirming the key SS18-SSX interaction with TLE1 in synovial sarcoma cells and patient samples." (PMID 27120803, 2016). "Co-immunoprecipitation analyses further demonstrate that the interaction of SS18-SSX with TLE1 is specific to synovial sarcoma, as SS18-SSX is pulled down with TLE1 exclusively in synovial sarcoma cell lines." (PMID 27120803, 2016). "In synovial sarcoma SS18-SSX replaces SSX18 in the BAF complex and evicts the tumor suppressor BAF47 that then undergoes proteasomal degradation." (PMID 27074562, 2016). "The top three available compounds capable of disrupting the SS18-SSX/TLE1 proximity ligation signal were validated in multiple synovial sarcoma cell lines." (PMID 27120803, 2016). "In an excised pulmonary metastasis, SS18-SSX/TLE1 complex co-localization signal is detected exclusively in synovial sarcoma tissue nuclei while the adjacent normal lung tissues are negative." (PMID 27120803, 2016). "EGR1 is repressed by the SS18-SSX fusion protein in synovial sarcoma in that SS18-SSX recruits PcG proteins, including EZH2 and Bmi1, to the EGR1 promoter and correlates with H3K27me338." (PMID 27125524, 2016). "The resulting SS18-SSX fusion oncogene can be detected in nearly all synovial sarcomas and is used clinically to confirm the diagnosis." (PMID 27120803, 2016). "A recent report suggests that a SS18-SSX fusion protein containing SWI/SNF complex in synovial sarcoma cell lines leads to displacement of PRC2/EZH2 at SOX2 loci, resulting in loss of the repressive H3K27Me3 marks and increased SOX2 expression." (PMID 27391784, 2016). "This suggests that SS18-SSX translocation containing synovial sarcoma cell lines are dependent on the activity of the PRC2 complex and EZH2 for their survival." (PMID 27391784, 2016).
synovial sarcoma (continued). "The characteristic t (X: 18)(p11.2; q11.2) translocation of synovial sarcoma fuses the SS18 gene on chromosome 18 to one of three homologous genes, SSX1, SSX2 or SSX4, which cluster on the X chromosome." (PMID 27074562, 2016). "The objective of this systematic review is to provide an up-to-date and unprecedented summary of the prognostic impact of SS18–SSX fusion type in synovial sarcoma." (PMID 26217552, 2015). "Many studies have reported the prognostic impact of SS18–SSX fusion type on synovial sarcomas, but it still remains a matter of debate." (PMID 26217552, 2015). "In synovial sarcoma a fusion of a SWI/SNF subunit (SS18) to SSX leads to the eviction of SNF5 from the complex and mis-localization of SWI/SNF ultimately resulting in inappropriate activation of a proliferative transcriptional program." (PMID 26716708, 2015). "Studies evaluating SS18–SSX fusion type as a prognostic marker in synovial sarcoma were systematically searched for in MEDLINE, EMBASE, and Web of Science." (PMID 26217552, 2015). "The 3′ region of the SSX-1, 2 and 4 genes are fused to nearly the entire SS18 gene in synovial sarcomas." (PMID 24787708, 2014). "Synovial sarcoma has a specific chromosomal translocation t(X; 18)(p11; q11) that leads to formation of an SS18-SSX fusion gene." (PMID 25165708, 2014). "Effect of tSS18 and tSSX truncated proteins on localization of SS18-SSX was examined in synovial sarcoma cells." (PMID 24130893, 2013). "Major fusion partners of SS18 in synovial sarcoma are SSX1 and SSX2, and SSX4 has been reported in rare cases." (PMID 24130893, 2013). "In patients with synovial sarcoma, specific chromosomal translocation of t(X; 18) (p11.2;q11.2) is observed, and SS18-SSX fusion protein expressed by this translocation is reported to be associated with pathogenesis." (PMID 24130893, 2013). "This suggests that the SS18-SSX fusion protein is specifically expressed in the synovial sarcoma cells, and is important in the pathogenesis of the disease." (PMID 24130893, 2013). "Some members of this family can become fused to the SS18 protein in synovial sarcoma (SS) through gene translocations, which is how these proteins were first identified." (PMID 20981248, 2010). "SS18 gene rearrangements were exclusively found in synovial sarcoma." (PMID 41562936, 2026). "No expression of Desmin, SMA, CD31, Caldesmon, TLE-1, WT-1, and SS18 was in the tumor, which could be differentiated from synovial sarcoma." (PMID 40831926, 2025). "Just as imatinib mesylate has been successful in treating the translocation-associated tumor chronic myeloid leukemia, developing drugs that effectively target the SS18-SSX fusion could provide new hope for synovial sarcoma patients." (PMID 41149817, 2025). "Synovial sarcoma belongs to the category of fusion gene-driven sarcomas, being defined by the chromosomal translocation t(X;18) (p11.2;q11.2), which leads to the formation of a fusion oncogene from which is expressed the fusion oncoprotein SS18::SSX." (PMID 40299558, 2025). "Furthermore, the stabilisation of β-catenin also contributes to SS18::SSX-driven synovial sarcoma, by increasing the transformation of mesenchymal progenitors, enhancing tumorigenesis." (PMID 40983796, 2025). "Importantly, it has been shown that the high expression of cell cycle genes is a key feature of a subset of undifferentiated cells in synovial sarcoma patient samples and that these genes are regulated by SS18::SSX fusions." (PMID 40804185, 2025). "Almost all patients with synovial sarcoma (SS) carry a characteristic gene fusion, SS18::SSX, which produces a disease-specific oncoprotein that is incorporated into the switch/sucrose non-fermentable (SWI/SNF) chromatin-remodeling complexes and profoundly alters their functionalities." (PMID 40267190, 2025). "Therefore, conducting FISH to investigate the status of SS18 translocation can exclude synovial sarcoma and is recommended before diagnosing spindle cell adamantinoma." (PMID 40249565, 2025).